TGFB1 (transforming growth factor beta 1)
Diseases named in the same sentence as TGFB1 in open-access papers (continued):
Sharing a sentence is not in itself a finding about the gene and the disease.
Alzheimer disease (146 papers, 2007 to 2026). A progressive, neurodegenerative disease characterized by loss of function and death of nerve cells in several areas of the brain leading to loss of cognitive function such as memory and language. "Understanding how TGFβ affects astrocyte development and function is of clinical relevance as overproduction of TGFβ1 from astrocytes is associated with cerebrovascular degeneration resulting in an Alzheimer’s disease-like phenotype." (PMID 30555301, 2018). "TGFβ1 has been strongly associated with microvascular alterations in Alzheimer’s disease." (PMID 26822027, 2016). "In addition, TGFb1 is a factor in responses to neurodegeneration: TGFb1 mRNA and protein were recently shown to increase in animal brains that cause local differentiation or neuronal death (which occurs in Alzheimer’s disease and DS)." (PMID 29244857, 2017). "By utilizing the ROC curve to assess the prognostic value of hub genes in the PPI network, 3 out of 5 shared hub genes, namely, CXCR4, MYH11, and TGFB1, showed potential indications as potential biomarkers for Alzheimer’s disease." (PMID 37705610, 2023). "We used genetically modified mice overexpressing the cytokine transforming growth factor beta 1 (TGF mice) that capture several aspects of the cerebrovascular pathology present in Alzheimer’s disease and vascular cognitive impairment and dementia." (PMID 38132326, 2023). "It is necessary in mediating microglial quiescence, while suppression of TGFβ1 expression and signaling is a commonality across Alzheimer’s Disease (human and mouse models), amyotrophic lateral sclerosis, multiple sclerosis, and depression." (PMID 33917279, 2021). "For example, TGFβ1 inhibits microglia chemotaxis towards amyloid beta aggregates observed in Alzheimer’s disease via activation of TGFβR/SMAD-2-mediated downregulation of the chemokine CCL5." (PMID 30940161, 2019). "Whereas TGFβ1 has protective and beneficial functions in cerebral ischaemia, it promotes the deposition of amyloid-beta plaques in models of Alzheimer’s disease." (PMID 22947253, 2012). "The suppression of the neuroprotective role of the signaling pathway TGFβ1 against Aβ toxicity in the diseased cell types may mechanistically explain Alzheimer’s disease." (PMID 38741048, 2024). "Significantly, TGFβ1 signalling counteracts the inhibitory effect of Aβ on NGF signalling, possibly supplementing the attenuated activity of NGF in Alzheimer's disease and representing a potential target for the development of anti-amyloid therapies." (PMID 22849569, 2012).
Nephropathy (142 papers, 2007 to 2026). A nonspecific term referring to disease or damage of the kidneys. "For example, a promoter polymorphism (-2518A/G) in the CCL2 gene was found to be associated with progressive kidney failure in Koreans with type 2 diabetes and TGFB1 T869C gene polymorphism showed association with nephropathy in type 2 diabetic Chinese patients." (PMID 19357773, 2009). "At the same time, rutin administration regulates renal function and reduces the degree of renal tissue damage in induced nephropathy by downregulating TGFβ-1 (transforming growth factor beta 1) and fibronectin expression." (PMID 38675115, 2024). "The initial role of TGFβ1 as a “first responder” led researchers to assume its involvement as a mediator of kidney damage." (PMID 38732588, 2024). "Overall, these results support, at least in part, the role of TGFβ1 as a mediator of accelerated and progressive nephropathy under diabetic conditions." (PMID 36430743, 2022). "Arginase-2 (Arg-2) and transforming growth factor-beta 1 (TGF-β1) are two markers of kidney damage by renal IR." (PMID 34829595, 2021). "According to a recent meta-analysis, patients with T2D and nephropathy (n = 1,604) exhibited increased serum and urine TGFβ1 levels." (PMID 31388341, 2019). "Parallel mechanistic studies reveal that HKC attenuates inflammatory cell activation and infiltration via p38 mitogen-activated protein kinase (MAPK) pathway inhibition, thereby reducing transforming growth factor beta 1 (TGF-β1) expression in nephropathy models." (PMID 41451365, 2025). "In the present study, we hypothesized that the overexpression of TGFβ1 is associated with insulin resistance and the rapid progression of TGFβ1-mediated nephropathy under diabetic conditions." (PMID 36430743, 2022). "In addition to increasing antioxidant enzymes, empagliflozin down-regulated gene expression of nephropathy markers (Hmox1, Ngal, Tgfβ1, Mcp-1), which are also involved in inflammatory and injury processes in the kidney cortex." (PMID 34638943, 2021). "First, activation of RAS induced by low salt and activation of TGFβ1 induced by CyA may increase DPP-4 activity, but tubulointerstitial injury and associated cell loss in proximal tubule cells (PTCs) is the prominent feature of CyA-induced nephropathy." (PMID 33803842, 2021). "Canonical IL-11 and TGFβ1 signaling stimulate myofibroblasts for the transient production of ECM, supporting TECs in completing the repair and achieving physiological resolution of kidney damage." (PMID 38732588, 2024). "After observing an up‐regulation of MXAR5 expression in human nephropathies characterized by kidney inflammation and fibrosis, we explored the potential regulation of MXRA5 expression by a representative fibrogenic cytokine TGFβ1 and a representative pro‐inflammatory cytokine, TWEAK." (PMID 27599751, 2017). "In resequencing the genes we identified eight novel variants for TGFB1, TGFBR1 and TGFBR2 genes but did not detect significant association between any of the common SNPs and nephropathy in this Caucasian population with type 1 diabetes." (PMID 17319955, 2007). "In nephropathy, activation of NFE2L2 reduces oxidative damage and negatively regulates TGFB1 & extracellular matrix production." (PMID 28761062, 2017).
type 2 diabetes (140 papers, 2007 to 2026). "In particular, according to our projection approach, genes TGFB1 and IL1B are good candidates for association with type 2 diabetes." (PMID 31845988, 2020). "TGFB1 was reported to be highly expressed in bone marrow mesenchymal stem cells (BMSCs) of type 2 diabetic rats; with TGFB1 inhibited, the osteogenic differentiation of BMSCs was enhanced, the aging of BMSCs delayed, the bone mass increased and the fracture healing promoted in the rats." (PMID 38509680, 2024). "It is unknown whether suppressed Tgfb1 mediates enhanced adipogenesis in the bone marrow in type 2 diabetes." (PMID 36307522, 2022). "Contrastingly, immunohistochemical displayed TGFβ1 has also been significantly suppressed, proving that VASH-1 has the inhibitory effect of renal interstitial fibrosis in type 2 diabetes." (PMID 32754616, 2020). "Treatment of type 2 diabetic rats induced by intraperitoneal (i.p.)injection of streptozotocin (STZ) with CM (35 ml/rat/day), reduced the level of transforming growth factor beta 1 (TGF-β1) which indicate anti-inflammatory activities." (PMID 35493477, 2022). "We tested association of nine single nucleotide polymorphisms (SNPs) from TGFβ1, TNFα, CCR2 and CCR5 genes among individuals with type-2 diabetes with and without renal insufficiency." (PMID 17428349, 2007).
Allergy (135 papers, 2008 to 2025). An allergy is an immune response or reaction to substances that are usually not harmful. "Recent studies have demonstrated that disruption in TGFβ1 signaling imposes a strong predisposition for human allergic diseases." (PMID 24795504, 2014). "Numerous studies have shown that Treg cells as main producers of Transforming Growth Factor beta 1 (TGFβ1) and Interleukin 10 (IL-10) play an important role in protecting against allergic diseases, thus the alteration in Treg cells is associated with eosinophilic allergy." (PMID 33868606, 2021). "If methylation in genes that control Treg function (e.g., FOXP3, IL-10, TGFβ1) increases, it can reduce gene activity, contributing to the development of allergies." (PMID 41176788, 2025). "Our second novel addition in Europeans is the TGFB1 rs1800471 missense variant that significantly alters the inhibitory action of TGFB1 protein molecule during allergic reactions." (PMID 37510360, 2023). "On the other hand, TGFβ1 is a cofactor of innate lymphoid cells to induce type-2 airway inflammation and key features of allergic diseases." (PMID 33936062, 2021). "Thus, studies on the cross-regulation between AhR and TGFβ1 signaling might be essential for better understanding of the underlying mechanisms for the synergic effects between environmental chemicals and allergens on the development of allergic diseases." (PMID 24795504, 2014). "However, hypermethylation of TGFB1 itself was observed in our nasal methylome analysis for allergic asthma and FeNO, suggesting that TGF-β signaling is altered in current disease or with concomitant elevated allergic disease biomarkers." (PMID 31300640, 2019). "Taken together, we suggest that AhR plays a role in modulating cockroach allergen-induced immune responses by controlling the active TGFβ1 release, and there is a possible synergistic effect between exposure to allergens and environmental chemicals on the development of allergic diseases." (PMID 24795504, 2014). "Hence, it remains unknown whether the decrease in TGFB1 transcription is related to the fact that DEHP attenuates the immune response or to the fact that TGF-β1 is already decreased in allergy mucosa." (PMID 19057701, 2008).
pulmonary hypertension (135 papers, 2011 to 2026). Increased pressure within the pulmonary circulation due to lung or heart disorder. "Variants in TGFB1 might affect its function and lead to pulmonary hypertension." (PMID 31382961, 2019). "We recently reported higher levels of TGFβ‐1‐loaded plasma‐derived EVs in HIV‐infected individuals with pulmonary hypertension with the ability to increase smooth muscle and endothelial dysfunction." (PMID 34262673, 2021). "Most recently, PIO has been reported to reverse pulmonary arterial hypertension, another type of PH, and reverse vascular remodeling via fatty acid oxidation, inhibiting transforming growth factor-β (TGFβ1) signaling and 5-HT receptor signaling." (PMID 33192545, 2020). "Other studies have shown that in mechanically stretched rat models of pulmonary arterial hypertension, the MAPK pathway is activated, mediating increased TGFβ-1 expression and leading to vascular remodeling and impaired cardiac function." (PMID 40997050, 2025). "Notably, high expression of TGFβ1 and phosphorylation of SMAD2/3 in the rat pulmonary hypertension model were reversed by eIF3a knockdown, and the expression of these proteins was also significantly greater in the AAV1-shRNA-NC group than in the control group." (PMID 40346622, 2025). "In patients suffering from pulmonary arterial hypertension, endothelin-1 (ET-1) synthesis is up-regulated and may increase PASMC activity and vessel wall remodeling through transforming growth factor beta-1 (TGF-β1) and connective tissue growth factor." (PMID 24015303, 2013). "It should be noted that high levels of TGFβ1 could induced a significant decrement of BMPR2 in human pulmonary microvascular blood vessel endothelial cells, while BMPR2 reduction sufficiently promotes EndMT in pulmonary arterial hypertension." (PMID 35582418, 2022).
leukemia (130 papers, 2007 to 2026). A malignant (clonal) hematologic disorder, involving hematopoietic stem cells and characterized by the presence of primitive or atypical myeloid or lymphoid cells in the bone marrow and the blood. "For instance, while acute lymphoblastic leukemia-derived exosomes inhibited the cytotoxicity of NK cells by enhancing TGFβ signaling, leukemia-derived exosomes activated the anticancer immune response by downregulating TGFβ1 expression." (PMID 36119094, 2022). "The in vitro action of TGFβ1‐mim was evaluated in human lung epithelial cells, Jurkat cells, and rat basophilic leukemia cells." (PMID 31750952, 2020). "KG-1a cells, human leukemia progenitors cell line which could respond to TGFβ1, were selected as a cell model for subsequent experiments." (PMID 37233879, 2023). "On the other hand, the analysis of leukaemia cell/CP fibroblast co‐cultures also showed that CD19+ blasts expressed IL1B, TGFB1, VEGFA, and the metalloproteinase ADAM10, and this expression was significantly upregulated in the presence of CP fibroblasts." (PMID 32686161, 2020). "It has been shown that the expression of transforming growth factor beta receptor (TGFβR) kinase on malignant cells, which is activated by bone marrow stromal cells-derived transforming growth factor beta 1 (TGF-β1), could enhance the DSB repair system in leukemia cells." (PMID 33781305, 2021). "Moreover, EVs derived from TGFB1-silenced leukemic cells, promoted DC activation, facilitated CD4+ T-cell proliferation and Th1 cytokine secretion, and further stimulated cytotoxic responses in lymphocytes and NK cells when compared to the control leukemia-EVs." (PMID 35493080, 2022).
pancreatic ductal adenocarcinoma (127 papers, 2009 to 2026). An infiltrating adenocarcinoma that arises from the epithelial cells of the pancreas. "The TG-interacting factor 1 (TGIF1) gene, which encodes a nuclear transcriptional corepressor of the TGFβ1/Smad signaling pathway, has been implicated in the pathogenesis of various types of human cancer; however, its role in pancreatic ductal adenocarcinoma (PDAC) has yet to be elucidated." (PMID 31109321, 2019). "Another study showed that neuropilin-1 can actively bind TGFβ1 and is involved in epithelial-to-mesenchymal transition processes in pancreatic ductal adenocarcinoma." (PMID 36672243, 2023). "LINC01638 overexpression increased TGFβ1, while silencing of LINC01638 markedly reduced TGFβ1 expression in pancreatic ductal adenocarcinoma cell line." (PMID 34178644, 2021). "The role of transforming growth factor beta-type-1 (TGFβ1) in pancreatic ductal adenocarcinoma (PDAC) progression is stage-dependent." (PMID 27895310, 2017). "Wang and colleagues could not identify a correlation between low PITX2 protein expression and methylation in pancreatic ductal adenocarcinoma but rather suggested that PITX2 acts as a tumor suppressor by inhibiting the TGFβ1-Smad4-pathway." (PMID 28617833, 2017). "The precise role of transforming growth factor beta type 1 (TGFβ1) in the progression of pancreatic ductal adenocarcinoma (PDAC) is unknown, and its relation to survival is context dependent." (PMID 27895310, 2017). "Pancreatic ductal adenocarcinoma (PDAC) cells are known for their high invasive/metastatic potential, which is regulated in part by the transforming growth factor β1 (TGFβ1)." (PMID 36289908, 2022). "Monocytes co-cultured with CAFs from pancreatic ductal adenocarcinoma have been shown to present with increased surface expression of specific M2-markers, e.g., CD163, CD200R, and CD206 surface receptors and up-regulation of ARG1, IL10, and TGFB1 genes." (PMID 31108906, 2019). "Indeed PP2 and PP1, but not SU6656, supressed TGFβ1-induced EMT in TGFβ-responsive Panc-1 pancreatic ductal adenocarcinoma cells whereas SFKs were required for basal and TGFβ1-induced cell migration." (PMID 25779657, 2015).
depression (125 papers, 2007 to 2026). "Studies have not shown a consistent relationship between plasma levels of TGFβ1 and depression, nonetheless, TGFβ1 appears to regulate inflammatory processes underlying MDD." (PMID 37252156, 2023). "The preclinical data suggest that impaired TGFβ1 signaling increases microglial activation and inflammation in depression." (PMID 37252156, 2023). "More recent developments have focused on understanding the clinical application of TGFβ1 in depression." (PMID 37252156, 2023). "Preliminary evidence supports that childhood maltreatment mediates a higher concentration of TGFβ1 in adults with major depressive disorder suggesting an epigenetic role for TGFβ1 in stress related disorders." (PMID 37252156, 2023). "Recently, TGF-beta signaling has been implicated in antidepressant effects of ketamine where reduced expressions of Tgfb1 and its receptors in a rodent model of depression was ameliorated by ketamine administration." (PMID 36543791, 2022). "Distribution of genotypes and alleles of rs1800469 (TGFB1), rs2070729 (IRF1), rs5275 (PTGS2), rs4648308 (PTGS2), rs2166975 (TGFA), rs5029748 (IKBKB) and the risk of depression occurrence." (PMID 32140313, 2020). "Gene-gene interactions of rs1800469 (TGFB1), rs2070729 (IRF1), rs5275 (PTGS2), rs4648308 (PTGS2), rs2166975 (TGFA), rs5029748 (IKBKB) and the risk of depression occurrence." (PMID 32140313, 2020). "Importantly to the current study, it has been suggested that pharmacological inhibition of transforming growth factor beta-1 inhibits depression." (PMID 35200304, 2022). "TGFβ1 levels are reduced in MDD, and TGFβ1 has been suggested as a pharmacological target for major depression." (PMID 37891842, 2023). "Third, i.c.v. injections of agomiR-132-5p caused depression-like behaviors through reduced expression of Bdnf and Tgfb1 mRNA in the PFC of control mice, indicating a role of miR-132-5p in depression-like behaviors." (PMID 36171191, 2022). "Administration of agomiR-132-5p decreased the expression of Bdnf and Tgfb1 in the PFC, resulting in depression-like behaviors." (PMID 36171191, 2022). "In the case of the impact of genotypes of the investigated SNPs on the episode severity measured using the Hamilton Depression Rating Scale (HDRS), significant differences was found between carriers of A/A and G/G genotypes of g.41354391A>G (rs1800469)—TGFB1." (PMID 32140313, 2020). "TGF-β exists in three isoforms, of which TGFB1 is the most widely studied in depression." (PMID 37252156, 2023). "In this research, we genotyped six polymorphic variants of TGFA, TGFB1, IRF1 and PTGS2 genes; and to our knowledge, none of this SNPs have been studied in the context of severity and treatment response in depression before." (PMID 32140313, 2020).